CD4 (CD4 molecule)
Diseases named in the same sentence as CD4 in open-access papers (continued):
Sharing a sentence is not in itself a finding about the gene and the disease.
tumor (continued). "Adding another layer of complexity, the MHC-II complex (encoded by HLA-DP, HLA-DM, HLA-DO, HLA-DQ, and HLA-DR) is canonically expressed by professional APCs to present antigens to CD4+ cells, but has also been found to be expressed by some tumor cells and to have an effect on ICB outcomes." (PMID 30497521, 2018). "Furthermore, this study aims to determine the correlation between the PD-L1 tumor cell expression and clinicopathological prognostic factors, lymphocyte density displaying PD-1, CD4, and CD8 expression in the tumor microenvironment in ccRCC series." (PMID 30144808, 2018). "Moreover, CD4 T cells derived from the tumor site of VTA-activated mice manifested elevated levels of the activation marker, CD69 (P < 0.001)." (PMID 30006573, 2018). "This favors activation of both CD8+ and CD4+ T cells and secretion of anti-tumor cytokines." (PMID 29301364, 2018). "We observed that CD3+ (a marker of T cells), CD8+ (a marker of cytotoxic T-cells), CD4+ (a marker of TH cells) and Foxp3+ (a marker of regulatory T cells) were negatively correlated with tumor size suggesting that most important is the T-cell immune response, lower is tumor grow." (PMID 30687269, 2018). "However, treatment with the addition of CD4+ T cells expressing the B7H6-specific CAR/T-bet (∆TBOX) improved survival despite tumor-bearing mice being treated with a single injection of these CAR T cells." (PMID 29515240, 2018). "Furthermore, genetic inhibition of autophagy in T cells leads to IL-9-dependent inhibition of tumor growth in mice bearing MC38 colon cancer and B16 melanoma and enhanced IL-9-producing CD4 tumor-infiltrating lymphocytes." (PMID 29867990, 2018). "Finally, in a mouse model of colon adenocarcinoma, the depletion of CD4+CD25+regulatory T cells with anti-CD25 antibodies enhances interleukin-2-induced anti-tumor immunity." (PMID 29915171, 2018). "Likewise, intratumoral injection of attenuated Salmonella reduced the percentage of CD25+FoxP3+ cells among spleen and tumor CD4+ T cells in a colon cancer model." (PMID 29765907, 2018). "Our results showed that Salmonella LVR01 plus CHOP chemotherapy induces a significant increase in gene expression of several chemokines at day 45 p.t.i., which it is consistent with the increased number of tumor-infiltrating cells (neutrophils, NK cells, and CD4+ and CD8+ T cells,) in those mice." (PMID 29410666, 2018). "The implication of this could be a decrease in a CD4+ T-cell mediated anti-tumor response, with a potentially diminished cellular (Th1/Th17) or humoral (Th2) immune function." (PMID 29513764, 2018). "Using flow cytometry analysis, we thus evaluated the impact of SVX treatment on the frequencies and phenotypes of CD8+ T cells, CD4+ FoxP3− Tconv, and CD4+ FoxP3+ Treg cells both in the spleen and among tumor infiltrating lymphocytes (TILs) of TB mice vaccinated or not with SVX but also in TF mice." (PMID 30483475, 2018). "The presence of AhR in tumor-infiltrating lymphocytes was confirmed by the use of CD4 antibodies." (PMID 29320557, 2018). "In order to determine whether anal glandular neoplasms meet this criteria, PD-L1 expression in epithelial (tumour) cells as well as intratumoural CD4+, CD8+, Foxp3+, and PD-1+ T cell densities were analysed by immunohistochemistry." (PMID 29700411, 2018). "Of note, the augmented anti-tumor immune response in Nr2f6−/− mice were linked to a markedly higher PD-1 and PD-L1 expression on CD8+ and CD4+ T-cell subsets in vitro when compared to wild-type animals, suggesting a potential resistance mechanism via upregulation of T-cell exhaustion markers." (PMID 29670099, 2018). "We could show a significantly enhanced tumor outgrowth in Nr2f6−/− mice treated with a combination of CD4+ and CD8+ depleting antibodies when compared to the IgG2b-treated Nr2f6−/− control group." (PMID 29670099, 2018).
tumor (continued). "Additionally, the reactivation of cellular senescence in tumors by Th1-cytokines derived from CD4 lymphocytes has been identified recently as an additional mechanism for controlling tumor growth." (PMID 29032503, 2018). "Recently, it is gradually recognized that some B-cell subpopulations including regulatory B cells can impair CD4+ T cell activation or produce cytokines promote tumor progression, Leading to dramatically suppress antibody and inhibit antitumor effector T cells." (PMID 30355653, 2018). "However, GSI treatment significantly reduced AhR mRNA expression in CD4+ T cells purified from tumor site (P<0.0001), while slightly decreased AhR expression in CD4+ T cells purified from nontumor site (P=0.006)." (PMID 30473538, 2018). "On the other hand, soluble HLA-G secreted by both tumor and immune cells may directly inhibit CD4+ and CD8+ T cell proliferation." (PMID 30574154, 2018). "NY-ESO-1 is considered as a safe and compatible tumor antigen in design of vaccine, due to its extensive presence in various tumor types and the strong spontaneous cellular immune responses including activation of CD4 and CD8+ T cells in the vitro and vivo study." (PMID 30127747, 2018). "The expression of Tim-3 on tumor cells may lead to tumor progression by multiple mechanisms, including direct suppression of CD4 T-cell function and inhibition of IL-6–STAT3 signaling and by directly promoting tumor metastasis." (PMID 29560265, 2018). "In this work, we demonstrate that tumors may set a dominant inhibitory environment in the TdLN, preventing efficient priming of tumor Ag-specific naive CD4+ T cells that instead become anergic or pTregs." (PMID 29844317, 2018). "Salmonella induced upregulation of Il2, Il4, Ifng, and Tnfa gene expression in the tumor, which might be involved in the intratumoral recruitment of CD4+ T, CD8+ T, and NK cells." (PMID 29410666, 2018). "Indeed, secretion of CXCL12 by activated PSCs reduces the migration of CD8+ and CD4+ T cells, NK cells, and Tregs to the juxtatumoral compartment within close proximity to the tumor." (PMID 29868007, 2018). "This suggests an alternative mechanism for ICB via CD4+ cell recognition of tumor antigens." (PMID 30497521, 2018). "We show that the IL-33/ST2 interaction is necessary for SCC progression, that it is involved in a mechanism during the recruitment of CD4+ T lymphocytes, dendritic cells, and macrophages in the tumor microenvironment, and that it promotes the production of IFN-γ, TNF-α, IL-10, and IL-17." (PMID 30112116, 2018). "Furthermore, consistent with our previous results, IL-17A was found to be significantly increased within the CD4+Foxp3− tumor infiltrated lymphocytes, suggesting that these ex-Foxp3 TH17 cells maintain their ability to produce pro-inflammatory cytokine." (PMID 30413714, 2018). "BC cells expressing more E-Cad recruited more functional CD4+ TILs in tumor microenvironment." (PMID 30069490, 2018). "Moreover, we found that the dLN-tumor overlapping clones were categorized into four patterns based on their frequencies in the dLN and tumor, and that anti-CD4 mAb treatment increased the proportion of tumorminor/dLNmajor and tumormajor/dLNmajor clones." (PMID 30733724, 2018). "In addition, silencing PD-L1 or PD-L2 specifically on DCs enhanced proliferation of tumor-specific CTLs and CD4+ T-cells, augmented production of IFN-γ, tumor-necrosis factor alpha (TNFα), IL-2, IL-5, and IL-12 and promoted cytolysis of tumor cells in vitro." (PMID 30568653, 2018). "Studies have proved that CD4+ T cells exert antitumor activities by activating and recruiting macrophages and eosinophils, which produce tumor-destroying free radicals and induce the secondary expansion and accumulation of CD8+ T cells by co-expressing IL-21 and IFN-γ38,39." (PMID 30120362, 2018).
tumor (continued). "To further investigate the mechanisms underlying the anti-tumor efficacy of ODN1826 or α-GalCer in the immunized mice that were injected with TC-1/A9 tumor cells, we depleted in vivo CD4+, CD8+, or NK1.1+ cells with monoclonal antibodies and MΦs by administration of carrageenan." (PMID 30469401, 2018). "Strategies designed to boost anti-tumor CD8+ CTL responses may therefore benefit from taking into account the CD4+ subset that appears most effective for their generation." (PMID 30505306, 2018). "Interestingly combination treatment increases tumor infiltrating CD4+T, CD8+T and NK+ cells and its therapeutic effect is abrogated by the in vivo depletion of any of these cell populations." (PMID 29844873, 2018). "Next, we questioned whether the Tag7-activated CD3+CD4+ lymphocytes are able to kill tumor cells that had escaped the immune control." (PMID 29850628, 2018). "Further, a significant increase of Il2 and Ifng gene expression was also observed in all treated groups; IL-2 and IFN-γ are key cytokines to develop effective immune responses, and the tumor-infiltrating CD4+ T cells are most likely one of the source of these cytokines." (PMID 29410666, 2018). "Interestingly, analysis of immune cells in the blood, spleen, and thymus of the non-tumor bearing a2V-KO mice revealed a significant decrease in CD4+ and CD8+ T cell populations." (PMID 30237863, 2018). "Moreover, NLRP3 signaling in macrophages drives the differentiation of CD4+ T cells into tumor-promoting T helper type 2 cells (Th2 cells), Th17 cells, and the Treg population, while suppressing Th1 cell polarization and cytotoxic CD8+ T cell activation." (PMID 30060755, 2018). "Tumor-infiltrating CD4+ T cells and CD8+ T cells displayed the similar phenotype in FASNhigh OvCa." (PMID 30619288, 2018). "Integrative data analysis using quantitative measurements of slides stained with a fluorescent 5-plex and chromogenic 3-plex revealed an immunosuppressive tumor microenvironment and adverse outcomes for patients with a low percentage of CD4+ and high percentage of PD1+/TIM3-/CD8+ T cells." (PMID 30619287, 2018). "We next measured the activity of tumor-associated CD4+ and CD8+ T cells in MC-38 tumor models." (PMID 29968710, 2018). "The anti-tumor activity of OX40 has been reported to be primarily dependent upon CD4+ T cells." (PMID 30563566, 2018). "We already showed that immunization with OMVs engineered with the EGFRvIII tumor-specific B cell epitope and with M30, a mutation-derived CD4+ T cell epitope expressed in B16F10 murine melanoma cells, fully prevented tumor growth in C57bl6 mice challenged with B16F10 cells expressing EGRFvIII." (PMID 30416985, 2018). "This analysis demonstrated that the addition of αCSF-1R both before and after the GVAX vaccination not only induced greater numbers of PD-1+ CD4+ or CD8+ tumor infiltrating T-cells in the “GVAX + αPD-1 + Pre/Post-αCSF-1R” group, but also increased the number and percentage of PD-1 + CD137+ T-cells." (PMID 30424804, 2018). "We hypothesized that these antibody responses had anti-tumor activity or it was indirectly related to other anti-tumor mechanisms, for example CD4 activation." (PMID 30478295, 2018). "There could also be a potential decrease in the CD4+ regulatory T cell population, in turn dampening the regulation of anti-tumor effector T-cell function." (PMID 29513764, 2018). "These tumor-derived exosomes also increased the secretion of the pro-inflammatory cytokines IL-1β, IL-6, and IL-10, and decreased the release of IFNγ, IL-2, and IL-17, both in CD4+ and CD8+T cells." (PMID 29515996, 2018). "Furthermore, in a spontaneous mouse model of mammary tumorigenesis, intratumoral CD4+ T cells produced cytokines, such as IL-4 and IL-13, which favor the activation and polarization of tumor-promoting immune cells, such as TAMs." (PMID 30355585, 2018).
tumor (continued). "In addition, CD4+ T cells were demonstrated to mediate tumor-antigen-mediated killing of tumor cells, highlighting the importance to understand the functional heterogeneity of the different T cell subsets in tumors." (PMID 30505306, 2018). "Intriguing studies suggest that antigen-specific CD4+ cells may assume cytotoxic anti-tumor capabilities following immune checkpoint blockade." (PMID 30285852, 2018). "Furthermore, ST2L+ regulatory T cellsfrom tumor tissue were also able to suppress CD4+CD25−T cellproliferation and interferon γ production." (PMID 29950152, 2018). "In a previous study, the antitumor effect of anti-CD4 mAb treatment was reported to be associated with augmented proliferation of tumor-specific CD8+ T cells using a TCR transgenic system; the effect of anti-CD4 mAb on the endogenous CD8+ T cell clones in the tumor-bearing host remained elusive." (PMID 30733724, 2018). "Activated macrophages might also induce tumour-specific CD4+ helper T cells, resulting in a relative reduction in Tregs." (PMID 29599915, 2018). "In addition, we observed more intense infiltration of CD8+ and CD4+ T cells into the tumour tissues of mice immunized with miPSDCs-CEA." (PMID 29545628, 2018). "Thus, the role of Mbd2 in controlling the CD4 and Ifng immune response is likely to be of great interest because ‘tumour‐promoting inflammation’ is now identified as an enabling characteristic in the hallmarks of cancer." (PMID 29603746, 2018). "For example, one could isolate just CD4+ T cells from FFPE tissues of a specific tumor microenvironment to explore their miRNA expression patterns and compare these patterns to that of other T cell subsets or T cells taken from a different tissue." (PMID 29955168, 2018). "Major histocompatibility complex-II antigen presentation is required to establish long-term memory anti-tumor immunity through stimulation of CD8+ T cells by CD4+ T cells inducing strong clonal expansion, cytokine production, tumor cell lysis, and T cell memory." (PMID 29867960, 2018). "Tumor infiltrating CD8/CD4 T cells demonstrated an effector phenotype and expressed PD1." (PMID 30400822, 2018). "Thus, CD4+ CAR T cells with increased T-bet expression have the potential to modify the tumor microenvironment and the immune response to better treat solid and hematologic cancers." (PMID 29515240, 2018). "CD4+ memory T cell responses were detected against a mutated IL-1βS230F peptide and two additional neoepitopes from HELZ2V241M and MLL2A4458V suggesting that efficient anti-tumor immune response occurred in this patient." (PMID 30459932, 2018). "While a significant increase in percentage of CD8β+ T cells was found at the tumor site (mean values: 39.7% in contrast to 13.3% for the PBMC samples), the proportion of CD4+ T cells expressing the CD8α+ activation molecule was significantly reduced within tumor isolates." (PMID 29930558, 2018). "CD8+ and CD4+ T lymphocytes are also differentially modulated by circulating tumor-derived EVs." (PMID 30583481, 2018). "Furthermore, a higher TGF-β concentration in tumor microenvironment was related to higher frequency of CD4+CD25+FoxP3+ cells, compared to peripheral blood of the same individual." (PMID 29785404, 2018). "Interestingly, the group of patients with an HPV-induced HNSCC have a much better prognosis than their HPV-negative counterparts and this was related to heavy tumor-infiltration by activated CD4+ and CD8+ T cells." (PMID 30192802, 2018). "Since we confirmed that the primary tumours induced the relocation of CD4+CD45+, CD8+CD45+, NK1.1+CD45+, CD11c+CD45+ and B220+CD45+HepELs in the lungs, we examined whether these cells expressed FX." (PMID 29930175, 2018). "Additionally, pre-treatment of neutrophil cultures with 2DG revealed that tumour-elicited neutrophils maintained a greater proportion of CD4+ T cell killing, following the inhibition of glucose metabolism." (PMID 30504842, 2018).
tumor (continued). "Nevertheless, an effective anti-tumour immune response is thought to be initiated by the taking up of tumour antigens by antigen-presenting cells (APCs) which in turn present them, and provide co-stimulatory signals, to both CD4+ and CD8+ T cells." (PMID 29875199, 2018). "Thus, after NPS-induced tumor clearance, protected rats expressed elevated levels of CD4 and CD8 Tem and Tcm lymphocytes." (PMID 29533981, 2018). "Remarkably, HLA class II‐restricted neoantigens have been identified as T‐cell targets in patients with HLA class II‐negative solid tumors 17, strongly suggesting that also neoantigens can be transferred from tumor cells to HLA class II‐positive APC for induction of specific CD4 T cells." (PMID 30011060, 2018). "While it is established that CD4+ T cells can be cytotoxic on their own, a major function lays in regulating trafficking, activation, proliferation, differentiation, and persistence of tumor-infiltrating cytotoxic CD8+ T cells." (PMID 30214445, 2018). "Here, the use of P. acnes as adjuvant for a hybrid tumor vaccine polarizes humoral and cellular immune responses to a Th1 pattern, enhances the cytotoxic activity of splenocytes toward tumor cells and increases the absolute number of CD4 and CD8 memory T cells." (PMID 30300366, 2018). "Our experiment results also showed that hDKK1-hHSP70 vaccination could significantly decrease the percentage of CD4+CD25+Foxp3+ regulatory T cells in tumor-bearing mice." (PMID 29416605, 2018). "Thus we were not able to assess relative impact of PD-1 expression on CD8+ and CD4+ cells as well as PD-L1 expression on macrophages and tumor cells as they relate to anti-PD-1 response." (PMID 30285852, 2018). "The interaction of BTLA and HVEM suppressed cytokine production of tumor-infiltrating CD4+ T cell." (PMID 30116751, 2018). "Conversely, increased expression of the glycolysis gatekeeper hexokinase 2 in tumor cells facilitated tumor escape from CD4+ T cell-mediated immune surveillance, further corroborating the importance of metabolic competition between tumor-infiltrating lymphocytes (TILs) and tumor cells." (PMID 30131808, 2018). "Overall, these data suggest that host Tregs, enriched in tumor Ag-specific cells, generated/expanded during tumor development participate in the induction of anergy and the conversion of newly arriving tumor Ag-specific naive CD4+ T cells into pTregs in the TdLN." (PMID 29844317, 2018). "Altogether, these results demonstrate the capacity of SVX vaccine to reshape the tumor microenvironment by strongly increasing the tumor infiltration of both CD4+ Tconv and CD8+ T cells over Treg cells therefore tipping the balance toward an efficient immune response." (PMID 30483475, 2018). "Features that define an immunologically hot or T-cell-inflamed tumor are becoming increasingly complex with evidence to support a role for CD4+ T-cells, T-regulatory cells, and myeloid-derived suppressor cells in contributing to a TME that is responsive to PD-1/PD-L1 blockade." (PMID 29357948, 2018). "Similarly, the anti-tumor effectors T cells (CD4+ and CD8+) have the potential to block the formation of a new set of tumors." (PMID 29568324, 2018). "After planned administration, the number of tumor-infiltrating CD4+ and CD8+ T cells increased from 22 to 30.8% and from 4.8 to 8.6% respectively in diosgenin-treated cohort, while that increased to 27.6 and 17.5% respectively in combined administration cohort." (PMID 30305604, 2018). "On the contrary, antibody depletion of CD4+ cells increased the anti-tumor response." (PMID 30469401, 2018). "Three types of T cells were observed in tumor: CD4+, CD8+, and CD4−CD8− DN T cells." (PMID 30774636, 2018). "Tumor regression after Myc inactivation is associated with a not fully understood immune response, as reflected by the accumulation of CD4 + T cells." (PMID 29765155, 2018).